MMP2 (matrix metallopeptidase 2)
Diseases named in the same sentence as MMP2 in open-access papers (continued):
Sharing a sentence is not in itself a finding about the gene and the disease.
diabetic retinopathy (26 papers, 2009 to 2024). "Diabetic retinopathy, a microvascular complication of DM, is also reported to be associated with an increased level of MMP-2 and -9 in aqueous humor, which was correlated with protein concentration, being essential for retinal neovascularisation assessment." (PMID 30818888, 2019). "Additionally, increased MMP-2 has been suggested to be associated with diabetic retinopathy through pathological retinal neovascularization." (PMID 39685536, 2024). "Taken together, our data show that RMP relative location with ECs is involved in the integrity of iBRB via MMP-2/9 and has important implications for treating diabetic retinopathy and other retinal disorders involving iBRB dysfunction." (PMID 34630739, 2021). "In experimental models of DM, increased oxidative stress activates MMP-2, and antioxidant therapies inhibit the development of diabetic retinopathy by modulating retinal MMP-2 levels." (PMID 32093214, 2020). "MMP-2 was also previously investigated in the aqueous humor of the eyes of patients with diabetic retinopathy, and increased activity was detected in patients with diabetic retinopathy vs. patients free from this complication." (PMID 31936869, 2020). "In contrast to their involvement in early stages of diabetic retinopathy, increased levels of MMP-2 and MMP-9 facilitate angiogenesis in the later stage of the disease through multiple proposed mechanisms." (PMID 31398819, 2019). "The vascular endothelial growth factor (VEGF) and matrix metalloproteinases (MMP)-2 have also been used as targets for neovascularization inhibition in diabetic retinopathy." (PMID 27916864, 2016). "Several studies have shown that MMP-2 is a key molecule in diabetic retinopathy." (PMID 32455133, 2020). "In the early stage of diabetic retinopathy, increased levels of MMP-2 and MMP-9 may promote vascular permeability by degrading tight junction proteins, thus disturbing the tight junction complex." (PMID 31398819, 2019). "In addition, the three microalgae and nutritional ingredients reduced mRNA expression levels of VEGF and MMP-2, which are critical steps involved in the pathogenesis of diabetic retinopathy." (PMID 27916864, 2016). "In addition, MMP2 in retinal capillary cells was activated by superoxide in the development of diabetic retinopathy." (PMID 25333278, 2014). "The ethanol extract of Dendrobium chrysotoxum Lindl ameliorates retinal angiogenesis during the development of diabetic retinopathy via inhibiting the expression of VEGF/VEGFR2 and other proangiogenic factors such as MMP-2/9." (PMID 33777140, 2021). "For instance, circ_0005015 elevates the expression of MMP-2, XIAP, and STAT3 thereby promoting the development of diabetes retinopathy via acting as a molecular sponge of miR-519d-3p." (PMID 32600379, 2020). "Activation of MMP-2 and MMP-9 is important in pathogenesis of diabetic microangiopathic complications such as diabetic retinopathy, nephropathy, and neuropathy." (PMID 32093214, 2020). "For example, levels of MMP-2 and MMP-9 were significantly higher in the retina and vitreous of diabetic retinopathy patients and animal models." (PMID 31398819, 2019). "MMP-2 and -9 expressions might be made via the Ras/Raf ERK1/2 and PI3K/ Akt/mTOR pathways to induce diabetic retinopathy." (PMID 27154195, 2016). "In addition to that, NXT reduces the development of diabetic retinopathy involved in inhibition of the expression of CAS-3, MMP-2/9, and TNF-α." (PMID 27668004, 2016). "MMPs may be activated by ROS in patients and animal models with diabetic retinopathy, which have shown increased MMP-9 and MMP-2 in their retina and vitreous." (PMID 27154195, 2016). "Some processes relevant to diabetic retinopathy were found upregulated in diabetic aqueous samples including CD40, C reactive protein, erythropoietin, fatty acid binding protein, FGF basic, fibrinogen, IL-1ra, IL-8, leptin, macrophage-derived chemokine (MDC), MMP-2, and VEGF." (PMID 19145248, 2009).
diabetic retinopathy (continued). "Inhibition of MMP-9 and MMP-2 with COX inhibitors prevents retinal pathologies, but there is no clinical study on the treatment of diabetic retinopathy patients with MMP inhibitors." (PMID 35729613, 2022).
coronary artery disease (25 papers, 2008 to 2025). "Coronary artery disease (CAD) has also been associated with MMP-2." (PMID 30794673, 2019). "Furthermore, specific haplotypes based on SNPs in the promoter region of the MMP-2 gene were associated with coronary artery disease." (PMID 18552985, 2008). "Coronary heart disease is closely related to vascular wall calcification, particularly in the tunica intima which involved the actions of matrix metalloproteinase 2 (MMP-2)." (PMID 36292250, 2022). "Most of these papers employ MMP-2 as a potential biomarker for ischemic heart diseases or as a therapeutic target to evoke cardioprotection." (PMID 29674965, 2018). "We have demonstrated that MMP-2 can be a promising biomarker for patients with coronary artery disease." (PMID 29674965, 2018). "Since all participants of our study group had coronary artery disease and only those suffering from DM had elevated plasma MMP-2, an important observation is that DM was a strong determinant of increased plasma MMPs." (PMID 28770228, 2017). "Prex1 and Irx3 are suggested as potential modifier genes of cardiac Cu content, while Ctsa, Mmp2, and Armcx1 may closely be related to ischemic heart disease." (PMID 36818345, 2023). "The plasma levels of MMP-1, MMP-7, MMP-8, MMP-9, and MMP-10 are elevated in patients with coronary artery disease (CAD), whereas those of MMP-2 and MMP-3 levels are decreased." (PMID 36142454, 2022). "Increased expression levels of MMP-2 and MMP-9 were confirmed in the expansively remodeled plaques of patients who died from coronary artery disease." (PMID 36142454, 2022). "We have previously shown that MMP-2 activity correlates positively with serum total (r = 0.55; p < 0.05) and LDL cholesterol levels (r = 0.45; p < 0.05) in coronary artery disease patients." (PMID 32977437, 2020). "Elevation of plasma MMP-2, MMP-9 or both have been observed in coronary heart disease, polypoidal choroidal vasculopathy and Japanese encephalitis." (PMID 27352030, 2016). "The reason for the opposing direction of change is unexplained, but precedent exists for differential patterns of MMP-2 and MMP-9 gene expression in coronary heart disease, chronic obstructive pulmonary disease, and thoracic aortic aneurysm." (PMID 27352030, 2016). "A prospective cohort study in non-diabetic patients with coronary artery disease concluded that elevated serum MMP-2, -3, and -9 were predictive of more rapid eGFR decline." (PMID 39123230, 2024). "Elevated plasma levels of MMP-2 and MMP-9 in coronary heart disease patients correlate with plaque instability and the severity of acute coronary syndrome, making them valuable for predicting these events and diagnosing chronic total occlusion of the coronary artery." (PMID 39200884, 2024). "We showed that diabetic patients with coronary artery disease presented significantly higher plasma levels of MMP-2, but not MMP-9, than nondiabetic counterparts." (PMID 28770228, 2017). "Moreover, over-expressions of MMP-2, -3, and -9 are found in human atherosclerotic plaque, and their plasma levels have been identified as a novel predictor of long-term prognosis and cardiovascular mortality in coronary artery disease (CAD) patients." (PMID 23922934, 2013). "As one of the highest incidences of CVDs, coronary artery disease links with more than 20 targets in this T-cD network, such as VCAM1 and ICAM1 (reported to increase in dysfunctional endothelial cells), MMP9, MMP3, and MMP2 (being influencing factors in cardiac fibrosis)." (PMID 29861771, 2018).
retinoblastoma (25 papers, 2013 to 2025). A malignant tumor that originates in the nuclear layer of the retina. "Higher MMP-9 expression is associated with a more advanced stage of disease; MMP-2 is believed to regulate the differentiation of retinoblastoma cells via the activation of ERK1/2 pathway." (PMID 35457074, 2022). "Eriodictyol, a natural dihydroflavonoid, caused significant inhibition of migration and invasion of retinoblastoma cells; this resulted from downregulation of MMP-2 and MMP-9 protein expression and blockage of the Akt and PI3K signaling pathways." (PMID 35457074, 2022). "MMP2 and MMP9 have been implicated in promoting cell migration, viability, and the secretion of angiogenic factors in retinoblastoma cells." (PMID 40332443, 2025). "Our observations align with a previous study on retinoblastoma (RB) that investigated the effects of inactivating MMP‐2 or MMP‐9 in cell migration, invasion, and angiogenesis." (PMID 38064181, 2023). "Immunohistochemical analysis of primary Rb tumors show that MMP-2 and MMP-9 protein levels are higher in samples that had invaded the optic nerve." (PMID 28633655, 2017). "Researchers have recently demonstrated that MMP-2 activity is directly involved in the differentiation of retinoblastoma cells." (PMID 23129147, 2013). "The inhibition of MMP2 decreases cellular migration in in vitro models of retinoblastoma." (PMID 36559076, 2022). "For example, in retinoblastoma, MMP2 and MMP9 degrade type IV collagen to facilitate invasion." (PMID 31579438, 2019). "CD147 plays a role in the up-regulation of MMP-2 in invasive retinoblastoma." (PMID 25268615, 2014). "They concluded that, ‘therapeutics targeting to MMP-2 may prove useful for reducing malignancy through the differentiation of retinoblastoma cells’." (PMID 23129147, 2013). "Indeed, MMP2 can be directly regulated by FOXM1 in human retinoblastoma Y-79 cells." (PMID 38338955, 2024). "Furthermore, inhibition of MMP-2 significantly reduced secretion of TGF-β1 in both Rb models." (PMID 28633655, 2017). "The levels of MMP-1, MMP-2, and MMP-9 have also been found to have a significant positive correlation with the intensity of retinoblastoma invasion and the occurrence of metastases." (PMID 35457074, 2022). "Microarray analysis have detected an upregulation of FOXM1 in human retinoblastoma, and in retinoblastoma Y79 cells, FOXM1 depletion has been shown to affect cell invasive capacity by targeting MMP2." (PMID 33953844, 2021). "Expression of MMP-2 and TIMP-2 was also studied in retinoblastoma (RB), the most common primary malignant intraocular cancer in children." (PMID 32751899, 2020). "The results confirm that MMP-1, MMP-2, MMP-9, and VEGF overexpression is highly related to poor retinoblastoma differentiation and tumor invasion." (PMID 31311559, 2019). "MMP-1, MMP-2, MMP-9 and VEGF play important roles in the development and progression of retinoblastoma." (PMID 31311559, 2019). "Collectively, our data indicates MMP-2 and MMP-9 drive metastatic pathways, including migration, viability and secretion of angiogenic factors in Rb cells." (PMID 28633655, 2017). "Our work focuses on MMP-2 and MMP-9 activity in Rb, the most common intraocular malignancy in children." (PMID 28633655, 2017). "In conclusion, SUZ12 siRNA inhibited cell invasion and the expression of VEGF, MMP-2 and MMP-9 in SO-RB50 retinoblastoma cells." (PMID 25295075, 2014). "In retinoblastoma, knockdown of SUZ12 reduced MMP2/9 protein expression." (PMID 39400513, 2024). "Interestingly, the selective inhibition of MMP-2 and MMP-9 in retinoblastoma reduces the production of TGF-β1, the key factor for EMT, known to facilitate invasion and metastasis providing an insight into the wider role of MMPs." (PMID 35457074, 2022).
retinoblastoma (continued). "In addition, higher levels of MMP-2 and MMP-9 in retinoblastoma cells are associated with an elevated risk of optic nerve invasion by cancer, suggesting that they may be responsible for increased malignancy of retinoblastoma, and their presence indicates the need for more aggressive therapy." (PMID 35457074, 2022). "Using inhibitors of MMP-2 (ARP100) and MMP-9 (AG-L-66085), the migration in metastatic Y79 retinoblastoma cells was inhibited, demonstrating that MMP-2 and MMP-9 could promote Y79 cancer cell migration." (PMID 35326412, 2022). "We concluded that the overexpression of MMP-1, MMP-2, MMP-9 and VEGF is highly related to poor retinoblastoma differentiation, tumor invasion and advanced clinical stage and, thus, have a role in predicting the prognosis of retinoblastoma patients." (PMID 31311559, 2019). "For example, MMP-9 and MMP-2 inhibition may reduce VEGF expression and, thus, angiogenesis in retinoblastoma cell lines." (PMID 31311559, 2019). "After comprehensive study, they found that MMP-2 and -9 are involved in stimulating cell migration and contributing to cell viability whereas MMP-9 played an additional role in Angiopoietin-2 production thus enhancing angiogenesis in retinoblastoma cells." (PMID 29233192, 2017). "Interestingly, Reinhard and co-workers indicate that the lowered mRNA expression of MMP-2 is associated with poorer prognosis and chemotherapy resistance in retinoblastoma; however, no such change was observed at the protein level of pro- or active-MMP-2." (PMID 35457074, 2022). "Based on the recent understanding of the importance of MMP enzymes in retinoblastoma it has also been suggested that differential expression of MMP-9 and MMP-2 could be a significant pathologic factor reflecting the biology of retinoblastoma and may also be used as a monitoring test." (PMID 23129147, 2013). "Scientists concluded that MMP-2 and MMP-9 drive metastatic pathways, migration, viability, and secretion of angiogenic factors in two cell lines representing the metastatic and nonmetastatic forms of retinoblastoma cells." (PMID 33182665, 2020).
lung disease (24 papers, 2005 to 2024). "P. aeruginosa has been shown to increase MMP-2 activity in CFBE41o- cells and a gain of functional MMP-2 and loss of function of TIMPs 1 and 2 are possible causes of epithelial damage in S. maltophilia lung disease." (PMID 32161586, 2020). "Gelatinases (MMP2 & MMP9) have been implicated in the pathogenesis of various lung diseases." (PMID 31842927, 2019). "Elevated MMP-9 and MMP-2 activities have been linked to numerous lung disorders." (PMID 30114253, 2018). "Both gelatinases have been implicated in the pathogenesis of inflammation-related lung diseases; we also reasoned that MMP-2 expression might be enhanced to compensate for MMP-9 deletion." (PMID 18007984, 2007). "Currently, MMP-9 and MMP-2 have been reported to be essential factors for the clinical pathology of pulmonary disorders." (PMID 38047016, 2023). "Elevated levels of NFκB and metalloproteinases (MMP) (i.e., MMP-2 and MMP-9) are also known to be associated with increased NE activity and CF lung disease." (PMID 33546140, 2021). "Elevated levels of NFkB and metalloproteinases (MMP), namely MMP-2 and MMP-9, are associated with increased NE activity and CF lung disease pathogenesis and progression." (PMID 33546140, 2021). "MMP2, as a member of the matrix metalloproteinase family, shows an increasing trend in the acute and chronic phases of lung disease." (PMID 34136532, 2021). "Gelatinases MMP2 and MMP9 are capable of cleaving type IV collagen present in the basement membrane and have been implicated in a variety of pulmonary diseases." (PMID 22496659, 2012). "MMP-2 (gelatinase A) is produced by a wide range of cell types in the lung, and it is increased in lung disorders with oxidative stress and inflammation etiologies." (PMID 18007984, 2007). "Its impact on HLFs goes beyond MIF, including the stimulation of COX-2, IL-6, and MMP-2 expression, along with the synthesis of PGE2 implicated in inflammation and remodeling of the ECM, processes that play significant pathogenetic roles in lung diseases." (PMID 38145300, 2024). "The impact of PDE4 inhibitors on MMP expression and/or activity has been previously reported, mostly in the context of pulmonary diseases, in which these drugs abolish the enhanced elastolytic activity driven by inflammatory stimulus and attenuate MMP-2 and/or MMP-9 levels." (PMID 33809405, 2021). "These authors also observed the localization of MMP-2 in regenerating alveolar epithelial cells covering intra-alveolar fibrotic areas in a study of bronchiolitis obliterans organizing pneumonia, which is a reversible fibrotic human lung disease." (PMID 15651999, 2005). "The activity of MMP-2 and MMP-9 has been widely studied in animals and humans, presenting itself as a promising diagnostic biomarker and therapeutic target in various pathologies, such as changes in the vascular system, ischemic lesions, neurodegenerative diseases, lung diseases, and cancer." (PMID 38612961, 2024). "Matrix metalloproteinases (MMPs), such as MMP-2, play a prominent role in the remodeling of the ECM, which is a main characteristic of various lung diseases." (PMID 38145300, 2024). "We compared the activities of MMP‐7 in blood and MMP‐2 and ‐9 in BALF of CIPF dogs, dogs with other lung diseases, and healthy dogs." (PMID 33274549, 2021). "Interesting, BALF MMP-2 and TIMP-2 showed a high sensitivity and specificity in predicting the malignant nature of pulmonary disease in both derivation cohort and validation cohort." (PMID 29113325, 2017). "Therefore, activation of MMP-2 and MMP-9 may play an important role in pulmonary diseases." (PMID 30616599, 2019). "The aim of the study was to explore the role of MMP-2 and MMP-7, such as vascular endothelial growth factor (VEGF) -C and -D in women with LAM, including patients with minor pulmonary disease (i.e., <10 lung cysts), and TSC with or without LAM." (PMID 33981713, 2021).